HLA-B (major histocompatibility complex, class I, B)
Diseases named in the same sentence as HLA-B in open-access papers (continued):
Sharing a sentence is not in itself a finding about the gene and the disease.
COVID-19 (continued). "HLA-B is known to exhibit significant genetic diversity among individuals and will influence one’s ability to recognize and respond to viral infection by COVID-19." (PMID 40429886, 2025). "We found that HLA-B –21 M/M genotypes were more prevalent in patients with moderate compared to severe COVID-19 (6.0% vs. 0.9%)." (PMID 39487235, 2025). "Our study provides evidence on differential nature of TCR clonal repertoire in 22.37% of HLA-B*15:01-positive COVID-19 patients who developed severe/critical disease in our cohorts, comparing to HLA-B*15:01-expressing individuals with mild COVID-19." (PMID 40892914, 2025). "The study identified significant HLA alleles, SNPs and haplotypes in the HLA-B, -C, -F, -DQA1, -DRB1, and -DRB5 genes associated with COVID-19 severity." (PMID 41012626, 2025). "Here, we investigated the influence of the HLA-B –21 M/T dimorphism in a cohort of 230 unvaccinated patients hospitalized with COVID-19 and requiring respiratory support." (PMID 39487235, 2025). "In this study, we investigated the effect of HLA-B and HLA-C mRNA expression levels on COVID-19 severity in positive COVID-19 individuals." (PMID 38674456, 2024). "Our work is expected to strengthen the understanding of the relationship between HLA and COVID-19 by providing insights into HLA-B and C expression levels across ethnic populations in South Africa among COVID-19-symptomatic and asymptomatic individuals." (PMID 38674456, 2024). "In a study consisting of 82 COVID-19-infected individuals from China, the frequencies of HLA-B*15:27 and HLA-B*40:06 were statistically higher in COVID-19-infected individuals than in healthy controls." (PMID 38667755, 2024). "We identified significant HLA alleles (according to the conventional nomenclature), SNPs and haplotypes in the HLA-B, -C, -F, -DQA1, -DRB1, and -DRB5 genes associated with COVID-19 severity." (PMID 39684907, 2024). "In this study, we observed that symptomatic COVID-19-infected individuals had significantly higher HLA-B mRNA expression than asymptomatic individuals." (PMID 38674456, 2024). "From the analysis of the two cohorts, HLA-B, -C, -DRB1 and -DRB5 were significantly associated with COVID-19 severity, whereas HLA-F and -DQB1 lost significance." (PMID 39684907, 2024). "On the basis of epidemiological analysis, the authors demonstrated that the prevalence of HLA-B*44 and C*01 correlates with COVID-19 spreading across Italy." (PMID 39768617, 2024). "By contrast, HLA-B*15:03 was predicted to protect against COVID-19 by presenting highly conserved SARS-CoV-2 peptides to T cells." (PMID 37468623, 2023). "Our result showed that HLA-B*52 frequency was higher in mild COVID-19 patients than in severe patients, implying the protective role of this allele against disease severity; the association persisted after age and sex adjustment." (PMID 38301089, 2023). "We next examined the association between HLA-B*15:01 and asymptomatic infection in the combined UCSF prospective longitudinal COVID-19 Host Immune Response Pathogenesis (CHIRP) and Long-term Impact of Infection with Novel Coronavirus (LIINC) cohort." (PMID 37468623, 2023). "The involvement of inflammation, HLA-C*04, and HLA-B*35 in COVID-19 severity highlights the potential roles of both the adaptive and innate immune responses against SARS-CoV-2." (PMID 37708194, 2023). "At HLA-B, the Bw4 motif was also reduced, and the C1 motif introduced by B*46:01 was increased in severe COVID-19." (PMID 36849422, 2023). "We observed that an age-dependent effect of HLA-B*51:01 carriage [odds ratio (OR)=0.48 (0.28-0.80), Pbonf <0.036] is protective against severe COVID-19." (PMID 35185875, 2022). "The comparisons showed that the HLA-B*57/MICA*A9 haplotype was more frequent in COVID-19 cases than in the population reference group but significance was lost upon Bonferroni correction." (PMID 35805975, 2022).
COVID-19 (continued). "In other previous studies, HLA-B*15:03 and HLA-B*15:21 were predicted to present the most antigens in patients with COVID-19." (PMID 36423013, 2022). "In the 2020–2021 pandemic of COVID-19, initial data showed that HLA-B*46:01 has the fewest predicted binding peptides to SARS-CoV-2 proteome, which causes COVID-19 syndrome." (PMID 35632439, 2022). "It has been demonstrated that individuals with the HLA-B*46:01 allele and the fewest binding peptides for SARS-CoV-2 show a particular vulnerability to COVID-19, as previously shown for SARS." (PMID 35664675, 2022). "Compared with healthy controls, a significantly higher frequency of HLA-B Bw4 was observed in COVID-19 (p < 0.0001), HIV (p = 0.0002) and HBV (p < 0.0001) cohorts." (PMID 36555106, 2022). "Regarding COVID-19 severity, the HLA-A*33, ACE1 Ins, and TMPRSS2 rs12329760T alleles were associated with protection against severe forms, while the HLA-B*38, HLA-C*6, and ApoE rs429358C alleles were associated with risk for severe forms of COVID-19." (PMID 35793369, 2022). "Cellular subtyping of these CD8+ NP105–113-B*07:02 T cells show a higher proportion of naive T cells in one HLA-B*07:02 healthy individual compared with predominantly T effector memory subtypes in patients with acute COVID-19 (n = 17)." (PMID 34853448, 2022). "HLA class I polymorphisms, such as HLA-B*46:01, HLA-B*07:03, and HLA-Cw*08:01, and HLA class II polymorphisms HLA-DRB4*01 and HLA-DRB1*12:02 have been associated with the predisposition to COVID-19." (PMID 35062298, 2022). "Next, we investigated peptide-specific CD8+ T cell responses in PBMCs isolated from HLA-A*02:01 or HLA-B*40:01 positive COVID-19 patients." (PMID 33664060, 2021). "HLA-A, HLA-B, and HLA-C genotypes of n = 111 deceased patients with COVID-19 (Moscow, Russia) and n = 428 volunteers were identified with next-generation sequencing." (PMID 33732261, 2021). "In a Chinese study, HLA-B*15:27 and HLA-C*07:29 were more frequent in COVID-19 patients vs. control subjects, with the results staying significant after correction." (PMID 33807915, 2021). "HLA-B*15:01 has previously been associated with asymptomatic SARS-CoV-2 infection in comparison to mild COVID-19 in nonhospitalized individuals of European ancestry." (PMID 40892914, 2025). "In conclusion, our findings do not support an association between the HLA-B –21 M/T dimorphism and COVID-19 severity, in contrast to previous reports." (PMID 40650195, 2025). "To date, no studies have reported any association between HLA-B*37 and either susceptibility to or severity of COVID-19." (PMID 40508150, 2025). "Our study thus provides evidence on the differential nature of the TCR clonal repertoire in 22.37% of HLA-B*15:01-positive COVID-19 patients who developed severe or critical disease in our cohorts, comparing to HLA-B*15:01-expressing individuals with mild COVID-19." (PMID 40892914, 2025). "SNP rs9501117 located at 6q27 was found as a shared SNP between PrCa and the two COVID-19 severity phenotypes (hospitalization and critical illness), while SNP rs2854005 (harboring HLA-B) located at 6q27 was found as a shared SNP between PrCa and all three COVID-19 phenotypes." (PMID 41210689, 2025). "However, fundamental questions remained on the abundance and clonotypic nature of CD8+ T-cell responses in HLA-B*15:01-positive patients who succumbed to life-threatening COVID-19." (PMID 40892914, 2025). "Ex vivo tetramer-enrichment in HLA-B*15:01+ COVID-19 patients across different disease severity states, from asymptomatic to severe and critical patients, revealed no numerical advantage for the presence of cross-reactive, central memory-like B15/S919-specific CD8+ T cells." (PMID 40892914, 2025). "The data suggest that, in addition to HLA-A and HLA-B-restricted T cells, HLA-C-restricted T cells may play an important role in controlling COVID-19." (PMID 40877317, 2025).
COVID-19 (continued). "Moreover, we identified several shared genes, such as HLA-B and CCHCR1, previously implicated in either COVID-19 or PrCa, which support the robustness of our findings and point to potential targets for diagnosis and therapy." (PMID 41210689, 2025). "The present finding of the significance of HLA-B*08:01 and DRB1*03:01 allows us to presume that one of the mechanisms of severe COVID-19 may be associated with autoimmune reaction." (PMID 39768617, 2024). "In this paper, we investigated the HLA-B and C expression levels across South African ethnicities and whether these expression level variations influence COVID-19 severity in a particluar ethnic group." (PMID 38674456, 2024). "HLA-B*46:01 has a low binding affinity to SARS-CoV-2 peptides, indicating that individuals with HLA-B*46:01 might have increased COVID-19 susceptibility." (PMID 38667755, 2024). "HLA-B*08, HLA-B*15:01, HLA-B*44, and HLA-B*51 positively correlated with COVID-19." (PMID 38667755, 2024). "A total of 3886 healthy individuals and 72 COVID-19-infected individuals were genotyped for HLA-B." (PMID 38667755, 2024). "Surprisingly, HLA-B mRNA expression was higher in younger individuals than older individuals; therefore, HLA-B might play a role in COVID-19 disease severity among younger individuals." (PMID 38674456, 2024). "It has been hypothesized that death from COVID-19 may be associated with immunogenetic markers including IL12B, along with HLA-B, IL6, and IL10." (PMID 36800980, 2023). "as a binder for HLA-B*1501 and revealed to be an immunodominant epitope in COVID-19 patients." (PMID 37275886, 2023). "It has also been reported that HLA-A*26:01 and HLA-B*51:01 were negatively associated, whilst HLA-A*03:01, HLA-DRB1*15:01, and the supertype B44 showed positive associations to COVID-19 severity in a cohort of patients who are citizens of the United Arab Emirates." (PMID 37708194, 2023). "Certain alleles, such as HLA-C*01C*03, B*08, A*25, B*44, B*51, and B*15:01, have been positively correlated with the incidence rate of COVID-19, while other alleles, such as HLA-B*18, B*14, and B*49, have shown negative correlation." (PMID 37048725, 2023). "Unsurprisingly, the “near to epithelial cell” myeloid population shows higher COVID-19 signatures score and highly expresses multiple MHC Class I and II related genes, such as B2M, HLA-A, HLA-B, HLA-C, HLA-E, and HLA-DRA, which are associated with the interferon (IFN) response." (PMID 37120608, 2023). "However, the frequencies of HLA-B-Bw4 alleles, either strong or weak binders for SARS-CoV-2 peptides, were both decreased in severe COVID-19." (PMID 36849422, 2023). "An in silico viral-peptide-MHC class I binding study has since found that HLA-B*46:01 had the fewest predicted binding peptides for the closely related SARS-CoV-2, suggesting that this allele may be particularly vulnerable to COVID-19." (PMID 37708194, 2023). "The frequency of HLA-B rare alleles was higher in individuals with severe COVID-19 (82.4%) regarding those with mild COVID-19 (54.2%; p = 0.0080; pc = 0.0400), but no significance in the comparison between mild and critical COVID-19 was achieved." (PMID 35960731, 2022). "Interestingly, IPS/FVS-cross-reactive T cells were detected in two out of two CMV+ HLA-B*35:01+ patients suffering from severe COVID-19, whereas the cross-reactive T cells were detected in 3 out of 37 healthy CMV+ HLA-B*35:01+ donors." (PMID 36408799, 2022). "According to an in silico analysis, coronavirus proteins bind to MHC-B*46:01 molecules with the lowest binding affinity, which is why carriers of HLA-B*46:01 genotype may be especially vulnerable to COVID-19, as was previously shown for SARS-CoV-2." (PMID 33802310, 2021). "This suggests that HLA-B mRNA expression levels are associated with increased disease severity, while HLA-C expression might not play a significant role in COVID-19 disease severity." (PMID 38674456, 2024).
COVID-19 (continued). "Taken together with the HLA-B*40:01 restricted binding of the PAM and ANXA7 peptides mimicked by SARS-CoV-2, the ALOX5AP splicing variant also mimicked by SARS-CoV-2 suggests the possibility of immune evasion or autoinflammation in HLA-B*40-constrained COVID-19 patients." (PMID 33024578, 2020). "Currently, we have studied the association of COVID-19 with STR in exon 5 of the MICA gene, HLA-B genes, and HLA-B/MICA haplotypes and in asymptomatic, moderate, and severe COVID-19 patients." (PMID 35805975, 2022). "An Italian study found that haplotype HLAA*01:01, HLA-B*08:01 and HLA-DRB1*03:01 contributed to the higher COVID-19 mortality in northern Italy." (PMID 36204639, 2022). "HLA-A*02 (n=24, 40%), HLA-A*01 (n=7, 11.7%), HLA-B*50 (n=6, 10%), HLA-B*35 and HLA-B*38 (n=5, 8.3%), HLA-DRB1*07 (n=12, 20%), and HLA- DRB1*04 (n=9, 15%) were most identified in all COVID-19 patients (n=30)." (PMID 36110850, 2022). "Several studies concluded that HLA-A*11:01, HLA-B*51:01, HLA-C*14:02, HLA-DQB1*06:02 and HLA-B*27:0 were correlated with a higher COVID-19 mortality." (PMID 36204639, 2022). "Higher frequencies for KIR2DS4 in severe COVID-19 patients and KIR3DS1+HLA-B*15:01+ in mild/moderate cases of COVID-19 than in control in Spanish indicate a potentially detrimental effect of activating KIR in COVID-19." (PMID 35273641, 2022). "Similarly, HLA class I molecules, such as HLAB*46:01, HLA-B*07:03, and HLA-Cw*08:01, as well as HLA class II molecules, including HLA-DRB4*01 and HLA-DRB1*12:02, are associated to predisposition to COVID-19, and some of these HLA molecules have been shown to bind to few SARS-CoV-2 peptides." (PMID 35062298, 2022). "To further corroborate these results, we generated peptide-loaded HLA-A*02:01 and HLA-B*40:01 tetramers presenting wild type and mutant peptides as a means to identify cognate CD8+ T cells from expanded PBMCs of HLA-matched COVID-19 patients." (PMID 33664060, 2021). "The unusual phenomenon of simultaneous occurrence of COVID-19 and SAT induced by SARS-CoV-2 infection can be HLA-dependent and related to the presence of homozygosity at HLA-B*35." (PMID 34960716, 2021). "In addition to the HLA-B -> HLA-E -> NKG2A axis, COVID-19 severity appears to be influenced by genetic variation in other NK cell receptors." (PMID 39487235, 2025). "HLA-B*44 was associated with the incidence of COVID-19 and HLA-B*35 was enriched in COVID-19 patients compared to controls, while HLA-B*40 and HLA-B*55 were enriched, but not statistically significant." (PMID 39487235, 2025). "Interestingly, several other non-celiac-associated HLAs are associated with asymptomatic (HLA-B*15:01, HLA-DRB1*04:01) or milder forms (HLA-B*15, HLA-DRB1*04) of COVID-19." (PMID 38138121, 2023). "Moreover, due to the close distance between HLA-B and -C loci, their expression may be considered together and accordingly, B*14:01-C*08:02 haplotype was one of the most frequent extended haplotypes in the group of mild COVID-19, as well as in the general Spanish population." (PMID 35960731, 2022). "We performed regression analysis between antigen coverage and the death rate due to COVID-19 across countries and found a negative correlation, although it was statistically significant only in HLA-B." (PMID 36423013, 2022). "This list included the HLA-B*40:01-restricted SARS-CoV-2-derived peptides GEAANFCAL, GEVITFDNL, and FIAGLIAIV which have been independently shown to induce T cell response, INF-γ production, and proliferation in COVID-19 patients." (PMID 35095907, 2021). "Our findings do not support a role for the HLA-B –21M/T dimorphism in modulating COVID-19 outcomes." (PMID 40650195, 2025). "Moreover, the risk effect of B*46:01 in COVID-19 was largely caused by its strong linkage disequilibrium (LD) with A*02:07, as in the absence of HLA-A*02:07, the frequency of HLA-B*46:01 alone was reduced in COVID-19 patients." (PMID 36849422, 2023).
COVID-19 (continued). "Furthermore, our prediction shows that HLA-B*46:01 is not binding to either the S or M protein-derived peptides, strengthening the reported general view that HLA-B*46:01 is not optimal for eliciting an immune response in COVID-19 patients." (PMID 32717854, 2020).
ankylosing spondylitis (72 papers, 2007 to 2026). An autoimmune chronic inflammatory disorder characterized by inflammation in the vertebral joints of the spine and sacroiliac joints. "Specifically, HLA-B*40:01 has been identified as a risk factor for ankylosing spondylitis, alongside HLA-B*27 alleles." (PMID 40693714, 2025). "For example, the HLA-B*27 polymorphism is strongly associated with ankylosing spondylitis, and HLA-DR*4 is a known risk factor for rheumatoid arthritis." (PMID 40155873, 2025). "Perhaps the most well-investigated is HLA-B*27:05 which has been associated with risk for ankylosing spondylitis, yet superior immune control of HIV and hepatitis C virus." (PMID 39967996, 2025). "Regarding ankylosing spondylitis (AS), a highly heritable and common rheumatic condition, the authors concluded that HLA-B*27:05, HLA-B*27:03, and HLA-B*27:06 are protective alleles, while most of the HLA-B*27 and HLA-B*60 alleles are susceptible alleles." (PMID 41614782, 2025). "The high prevalence of Ankylosing Spondylitis among individuals carrying the HLA-B*27 allele is a well-established observation, yet the exact molecular mechanism responsible for this association remains elusive." (PMID 38892265, 2024). "Among the independent signals, 15 are novel, including the association of HLA-B pos 138 variation with ankylosing spondylitis (AS), and rs9266290 and rs9266292 with allergy." (PMID 38702819, 2024). "Polymorphisms within the peptide binding groove were shown to govern the association of HLA-B*27 alleles with ankylosing spondylitis, HLA-A*29:02 with Birdshot uveitis, HLA-B*51 with Behçet disease and HLA-C*06:02 with psoriasis." (PMID 38596688, 2024). "The HLA-B*27:02 variant is considered a risk factor for ankylosing spondylitis, while HLA-B*27:07 appears to have a protective role against this pathology." (PMID 39201523, 2024). "Ankylosing spondylitis, psoriatic arthritis and other spondyloarthropathies exhibit strong association, HLA-B*27:05, suggesting a shared antigenic pathway of disease development." (PMID 37872223, 2023). "Background and Objectives: Ankylosing spondylitis (AS) is a chronic inflammatory disease and is highly linked with the expression of the human leukocytic antigen-B*27 (HLA-B*27) genotype." (PMID 36295572, 2022). "Distinct HLA-class I alleles with a strong associations with autoimmune diseases are HLA-B*27 that is associated with ankylosing spondylitis, HLA-C*06:02 with psoriasis, and HLA-B*51 with Behçet’s disease." (PMID 36700227, 2022). "Especially for HLA-B*27:05 associated with ankylosing spondylitis, more than 40% of the eluted peptides were cis- or trans-spliced products." (PMID 36700227, 2022). "Several groups of researchers examined the role of ERAP1 and ERAP2 as ankylosing spondylitis risk factors in addition to HLA-B*27 (reviewed by 17, 18, 26, 56–58)." (PMID 35769458, 2022). "Ankylosing spondylitis is strongly associated with HLA-B*27—90% of patients are positive, versus less than 10% in the healthy Europeans, e.g., in Poles." (PMID 35769458, 2022). "Consistent with this notion, ankylosing spondylitis‐disposing HLA‐B*27 and the Behçet's disease‐associated HLA‐B*51:01 immunopeptidomes are significantly altered in the absence of functional ERAP1." (PMID 34310018, 2021). "Although HLA-B*40:01 and HLA-B*40:02 are protective for autoimmune hepatitis, these alleles are associated with ankylosing spondylitis (AS)." (PMID 34447375, 2021). "This study was to investigate the polymorphism and distribution of alleles of HLA‐B*27 in patients with ankylosing spondylitis (AS) in Han population of southeastern China." (PMID 34499816, 2021). "We found that 5.3% Taiwanese were carriers of HLA-B*27:04, a risk factor for ankylosing spondylitis, and 4.1% of our population had HLA-B*15:02, known to be associated with carbamazepine-induced Stevens–Johnson syndrome 35,36." (PMID 33574314, 2021).